BSCL2 (BSCL2 lipid droplet biogenesis associated, seipin)
Description:
Mediates the formation of lipid droplets during the differentiation and maturation of adipocytes. Together with LDAF1, defines the sites of lipid droplet formation in the endoplasmic reticulum and promotes the aggregation of triacylglycerol molecules to form the core of a lipid droplet (nucleation) in the endoplasmic reticulum and drive budding of lipid droplets into the cytoplasm. BSCL2 and LDAF1 also regulate protein and lipid delivery from the endoplasmic reticulum into growing lipid droplets. During early adipogenesis, BSCL2 inhibits GPAT3 and GPAT4 activity, thereby preventing phosphatidic acid accumulation that could antagonize PPARG and block differentiation (By similarity). This inhibition is then relieved by ADIG during adipocyte maturation, allowing expansion of lipid droplets (By similarity). Regulates the maturation of ZFYVE1-positive nascent lipid droplets and the function of the RAB18-ZFYVE1 complex in mediating the formation of endoplasmic reticulum-lipid droplet contacts. Binds anionic phospholipids including phosphatidic acid.
Synonyms: seipin; GNG3LG; HMN5; HMN5C; HMND13; PELD; SPG17
Tractability: Antibody: UniProt predicts a signal peptide or a membrane-spanning region. PROTAC: ubiquitination databases record sites on it; its protein half-life has been measured.
Gene: Protein-coding gene on chromosome 11 (62,689,289 to 62,709,845, reverse strand). Ensembl gene ENSG00000168000.
Subcellular location: Endoplasmic reticulum membrane; Lipid droplet
Gene Ontology:
Molecular function: phospholipid binding; protein binding
Biological process: lipid droplet formation; lipid droplet organization; lipid storage; fat cell differentiation; negative regulation of lipid catabolic process; positive regulation of cold-induced thermogenesis
Cellular component: endoplasmic reticulum membrane; lipid droplet; endoplasmic reticulum
Genetic constraint (gnomAD): Loss-of-function variants: 42 observed, 62.54 expected, observed/expected ratio (o/e) 0.67, 90% interval 0.52 to 0.87. The upper end of that interval is the gene's LOEUF score, 0.87, which puts it in group 3 of 6, group 1 being the genes least tolerant of losing a copy. Missense variants: 539 observed, 608.97 expected, observed/expected ratio (o/e) 0.89, 90% interval 0.82 to 0.95. Synonymous variants: 237 observed, 237.63 expected, observed/expected ratio (o/e) 1, 90% interval 0.9 to 1.11.
Gene-disease validity (ClinGen):
ClinGen rates the evidence that BSCL2 causes each of these diseases.
distal hereditary motor neuropathy (autosomal dominant): Definitive.
lipodystrophy (autosomal recessive): Definitive. A congenital or acquired disorder characterized by abnormal loss or redistribution of the adipose tissue in the body.
Homologues: Orthologues: chimpanzee BSCL2 (99% identical), macaque BSCL2 (98% identical), dog BSCL2 (89% identical), pig BSCL2 (86% identical), mouse Bscl2 (84% identical), rabbit BSCL2 (82% identical), rat Bscl2 (81% identical), guinea pig BSCL2 (66% identical), zebrafish bscl2 (40% identical), tropical clawed frog bscl2 (39% identical), zebrafish bscl2l (35% identical), Drosophila melanogaster Seipin (25% identical), and 1 more.
Diseases named in the same sentence as BSCL2 in open-access papers:
BSCL2 is named in the same sentence as 93 diseases in open-access papers, as found by Europe PMC text mining. Sharing a sentence is not in itself a finding about the gene and the disease. The quoted sentences say what the papers report.
lipodystrophy (55 papers, 2011 to 2025). "Seipin, a protein encoded by the BSCL2 gene, plays a crucial role in lipid metabolism, and some pathogenic biallelic variants cause lipodystrophy and associated metabolic disorders." (PMID 41465464, 2025). "Several mouse studies have shown that Bscl2-deficient mice almost entirely reproduced the lipodystrophy (CGL) phenotype." (PMID 36830428, 2023). "AT-specific loss due to Bscl2 deficiency was also sufficient to induce generalized early-onset lipodystrophy." (PMID 36830428, 2023). "Global Bscl2‐deficient (Bscl2−/−) mice recapitulate human BSCL2 disease, exhibiting congenital lipodystrophy and severe insulin resistance." (PMID 35384404, 2022). "Congenital Generalized Lipodystrophy type 2 (CGL2) is the most severe form of lipodystrophy and is caused by mutations in the BSCL2 gene." (PMID 33498782, 2021). "BSCL2 gene mutations cause severe lipodystrophy, in which liver disease and infection are the main causes of death." (PMID 33498782, 2021). "Studies in a BSCL2 knockout mouse model showed that SEIPIN deficiency causes severe and consistent lipodystrophy with a dramatic loss of fat mass." (PMID 33147895, 2020). "Adipose tissue-specific loss of Bscl2 is also sufficient to cause early-onset generalised lipodystrophy in mice." (PMID 31848133, 2020). "This provides further evidence to suggest that Ad-B2(−/−) female mice are unable to safely store dietary lipids in adipocytes as a consequence of lipodystrophy caused by the ablation of Bscl2 specifically in adipose tissue." (PMID 30552349, 2018). "Overall, our data indicate that the loss of Bscl2 specifically in developing adipocytes causes lipodystrophy and ectopic lipid accumulation in the liver, along with significantly altered substrate utilisation in response to fasting and refeeding." (PMID 29459250, 2018). "The BSCL2, seipin gene mutation exhibits the most severe phenotype of lipodystrophy among the CGLs in human." (PMID 26690553, 2015). "The current study extends the body of evidence that describes the role of BSCL2 in congenital generalized lipodystrophy and association of loss-of-function mutations with severe lipodystrophy phenotype." (PMID 23659685, 2013). "The involvement of BSCL2 in lipodystrophy and neuropathy is associated with its expression in adipocytes and spinal cord motor neurons respectively." (PMID 23049863, 2012). "In humans, BSCL2 loss-of-function mutations cause a severe form of lipodystrophy, whilst a distinct set of gain-of-toxic-function mutations are associated with a heterogeneous group of neuropathies." (PMID 23049863, 2012). "Here we report the analysis of a Drosophila model of the most severe form of human lipodystrophy, Berardinelli-Seip Congenital Lipodystrophy 2, which is caused by mutations in the BSCL2/Seipin gene." (PMID 21533227, 2011). "Here we evaluate whether tissue-selective adeno-associated virus (AAV) vectors can provide a targeted form of gene therapy for lipodystrophy, using a preclinical lipodystrophic mouse model of Bscl2 deficiency." (PMID 39069561, 2024). "Of note, BSCL2 deficient rat are hypertriglyceridemic suggesting that rat could be a better model to study lipoproteins in the context of lipodystrophy." (PMID 35250856, 2022). "Consistently, under the adipocyte specific-promoter of the AdipoQ gene, CRE-mediated Bscl2 deletion leads to early (6 to 12 weeks of age) and severe lipodystrophy with a massive loss of gonadal and subcutaneous WAT and a 80% decrease in circulating adiponectin." (PMID 35054926, 2022). "A majority of patients with lipodystrophy presents hypertrophic cardiomyopathy as early as 6 months of age, as reported in a young girl with congenital generalized lipodystrophy due to seipin (BSCL2) mutation." (PMID 31656583, 2019). "Thus, lipodystrophy as a consequence of adipose-specific Bscl2 ablation remained insufficient to cause the severe metabolic dysfunction that is observed in global Bscl2 knockout mouse models." (PMID 30552349, 2018).
lipodystrophy (continued). "BSCL2 mutations in lipodystrophy patients result mostly in null alleles." (PMID 23740690, 2013). "BSCL2 mutations exhibit more severe lipodystrophy and metabolic alterations than AGPAT2 mutations." (PMID 23740690, 2013). "Furthermore, in a family of Pakistani heritage, a mutation in BSCL2 caused lipodystrophy." (PMID 36830428, 2023). "Nonsense mutations in Bscl2, the gene encoding Seipin, lead to a severe Congenital Generalized Lipodystrophy type 2 (CGL2) disease, clinically manifested with lipodystrophy, mental retardation and cognitive decline." (PMID 38773070, 2024). "Regarding the origin of lipodystrophy in the BSCL2 phenotype, in vitro experiments support that seipin is crucial for normal adipogenesis." (PMID 35250856, 2022). "Regarding lean mass, prior work in the same Bscl2-/- mice showed an increase in lean mass consistent with lipodystrophy." (PMID 35145475, 2021). "In models of classical lipodystrophy, such as global Agpat2-knockout mice or adipocyte-specific Bscl2-knockout mice, the body weights are usually lower than control littermate despite organomegaly." (PMID 32797353, 2021). "We directly sequenced all exons of genes associated with lipodystrophy including LMNA, ZMPSTE24, AGPAT2, BSCL2, CAV1, PTRF, and PPARγ2." (PMID 31293201, 2019). "For two lipodystrophy genes, BSCL2 and AGPAT2, sub-clusters with PLIN1 and CEBPA identifed by morphological similarity were validated by independent experiments as novel protein–protein and gene regulatory interactions." (PMID 30940487, 2019). "The restoration of Bscl2 expression selectively in adipocytes of Bscl2 knockout mice not only prevents lipodystrophy, but also insulin resistance and hepatic steatosis." (PMID 29459250, 2018). "We demonstrate that Ad-B2(−/−) mice display early onset lipodystrophy, in common with congenital Bscl2 null mice and CGL2 patients." (PMID 29459250, 2018). "The human lipodystrophy gene BSCL2 is known to be expressed in numerous tissues throughout the body." (PMID 29459250, 2018). "Re-expression of seipin in adipocytes under the control of the aP2 promoter in Bscl2 null mice rescues lipodystrophy, insulin resistance and hepatic steatosis." (PMID 29459250, 2018). "Although an obligate role for BSCL2 in lipid droplet biogenesis would appear at odds with the observations in this study, lipid droplets can occur in some cellular contexts even in BSCL2-related lipodystrophy, such as in severely fatty liver cells." (PMID 28982679, 2017). "The common duplication of PMP22 was ruled out by clinical-grade testing, and genes known to cause lipodystrophy (LMNA, PPARG, EMD, AGPAT2, BSCL2) were also sequenced." (PMID 28050599, 2017). "Mutations in several genes have been found in patients with inherited lipodystrophies, including mutations in LMNA, PPARG, AKT2 and ZMPSTE24 in partial lipodystrophy, and mutations in AGPAT2, BSCL2, CAV1 and PTRF in congenital total lipodystrophy." (PMID 26987365, 2016). "For instance, complete lipodystrophy is caused by mutations in caveolin-1 (CAV), seipin (BSCL2) or AGPAT218." (PMID 27225296, 2016). "What role does altered phospholipid levels play in the pathogenesis of lipodystrophies in patients with AGPAT2 and BSCL2/SEIPIN mutations?" (PMID 23740690, 2013). "BSCL2 is a severe form of lipodystrophy which affects adipocyte development and results in ectopic lipid storage in non-adipose tissues." (PMID 21533227, 2011). "Biallelic mutation in the BSCL2 gene can cause progressive encephalopathy with or without lipodystrophy (PELD; MIM: #615924) and congenital generalized lipodystrophy type 2 (CGL2; MIM: #269700)." (PMID 40092559, 2025). "Furthermore, the McIlroy and Rochford groups have restored human BSCL2 expression in global Bscl2-KO mice via AAV, which improved lipodystrophy-associated metabolic issues, an exciting application of gene therapy in lipodystrophy." (PMID 40663389, 2025).
lipodystrophy (continued). "At least ten lipodystrophy-associated genes have been identified, including phosphate acetyltransferase (AGPAT2), phosphoinositide-dependent serine-threonine protein kinase (AKT2), seipin (BSCL2), caveolin 1 (CAV1) and perilipin 1 (PLIN1)." (PMID 38454882, 2024). "It is known as the culprit for human CGL2/BSCL2, the most severe form of human lipodystrophy." (PMID 38525541, 2024). "Overall, our data indicate that loss of Bscl2 in hepatocytes in the background of lipodystrophy fails to cause metabolic dysfunction and the severe hepatic steatosis observed in global Bscl2 knockout mice." (PMID 31848133, 2020). "Mice lacking PRMT5 in adipocytes develop progressive lipodystrophy and insulin resistance, resembling BSCL2‐mutation disease." (PMID 33304767, 2020). "We next investigated whether the ablation of Bscl2 in hepatocytes in the background of lipodystrophy would lead to the development of hepatic steatosis that is commonly observed in the global Bscl2 knockout mouse models." (PMID 31848133, 2020). "However, lipodystrophy can be found in animal models with BSCL2 knockout and in human subjects with missense or nonsense mutations." (PMID 30402103, 2018). "We recently reported that adipose tissue-specific ablation of Bscl2 in male mice is sufficient to cause lipodystrophy, yet severe metabolic dysfunction does not manifest in this model." (PMID 30552349, 2018). "More than 30 recessive BSCL2 loss-of-function mutations are the cause of this lipodystrophy and it is still not clear if there is significant clinical difference among these kinds of mutations." (PMID 30402103, 2018). "PELD (Progressive Encephalopathy with or without Lipodystrophy or Celia’s Encephalopathy) is a fatal and rare neurodegenerative syndrome associated with the BSCL2 mutation c.985C>T, that results in an aberrant transcript without the exon 7 (Celia seipin)." (PMID 27391332, 2016). "While the inflammatory mechanism of lipodystrophy is relatively a new idea, overlapping aetiology between lipodystrophy and obesity might indicate that a platform of obesity treatment may well be applied to BSCL2 treatment." (PMID 25195639, 2014). "BSCL2 patients exhibit the most severe phenotype of lipodystrophy among the four BSCLs." (PMID 25195639, 2014). "Importantly, murine modelling of BSCL2 pathologies reveals significant functional conservation between humans and mice, such that whilst Bscl2 ablation leads to lipodystrophy the overexpression of an N88S mutant transgene promotes progressive motor deficits." (PMID 23049863, 2012). "BscL2 is an integral homo-oligomeric membrane protein in the endoplasmic reticulum that plays a role in the maturation of cytoplasmic lipid droplets Bscl2−/− mice develop severe white adipose tissue lipodystrophy, dyslipidemia, insulin resistance and hepatic steatosis." (PMID 33233602, 2020). "Therefore, we also examined whether the thermogenic activity of this tissue might protect mice from the metabolic consequences of lipodystrophy due to adipose specific Bscl2 ablation." (PMID 30552349, 2018). "In the last several years, many factors, including SEIPIN/BSCL2, Insulin receptor, AGPAT2, PPARγ, CIDEC, perilipin-1, and AKT-2, in white adipose tissue have been identified to regulate lipodystrophy or lipoatrophy in rodents." (PMID 35927268, 2022). "First of all, BSCL2 re-expression specifically in the adipocytes, through the aP2 promoter, is sufficient to correct the SKO mice lipodystrophy, insulin resistance and liver steatosis." (PMID 35250856, 2022). "BMI was lower after treatment in aggregated lipodystrophy, in generalized and partial subgroups, and in those with LMNA or BSCL2 mutations, but not PPARG or AGPAT2 mutations (Level 3 evidence)." (PMID 37794082, 2023).
lipodystrophy (continued). "Metreleptin use is associated with the lowering of triglycerides and haemoglobin A1c (HbA1c) in all lipodystrophy (n = 111), partial (n = 71) and generalised lipodystrophy (n = 41), and in LMNA, PPARG, AGPAT2 or BSCL2 subgroups (n = 72,13,21 and 21 respectively)." (PMID 37794082, 2023). "BSCL2 gene mutations result in genetic diseases including CGL2, progressive encephalopathy with or without lipodystrophy (also called Celia’s encephalopathy), and BSCL2-associated motor neuron diseases." (PMID 35740965, 2022). "LysM-B2KO mice failed to develop lipodystrophy and metabolic disease, providing a model to study the direct role of Bscl2 in myeloid lineage cells." (PMID 33498782, 2021). "Examination of the raw images of BSCL2/PLIN1 ablated cells revealed cells with decreased lipid accumulation overall, but with strikingly large residual lipid droplets as compared to control cells or cells ablated for other lipodystrophy genes such as PPARG." (PMID 30940487, 2019). "We have previously reported a new seipin-associated neurodegenerative syndrome (PELD, Progressive Encephalopathy with/without Lipodystrophy or Celia’s Encephalopathy, MIM:#615924) due to a c.985C>T mutation in BSCL2 gene." (PMID 27391332, 2016). "Indeed, adipose-specific ablation of Bscl2 in adult mice does not result in the severe lipodystrophy observed in SKO mice." (PMID 39069561, 2024). "Overall, these findings reveal that loss of Bscl2 specifically in developing adipocytes is sufficient to cause generalised lipodystrophy in early life in vivo, leading to several, but not all, clinical features observed in CGL2 patients and global Bscl2 knockout mice." (PMID 29459250, 2018). "This revealed that adipose, but not liver-selective re-expression of functional human BSCL2, is highly effective in restoring adipose development and metabolic health, thereby offering an effective and refined therapeutic intervention strategy for lipodystrophies." (PMID 39069561, 2024). "Although we speculated that the lack of lipodystrophy in that model may have protected against metabolic dysfunction, our data now provide strong additional evidence that Bscl2 is unlikely to play a cell-autonomous role in the liver, even in the presence of lipodystrophy." (PMID 31848133, 2020). "BSCL2, PTRF and LPIN1 lipodystrophy genes are not differentially expressed." (PMID 26176221, 2015).
Insulin resistance (20 papers, 2014 to 2025). Increased resistance towards insulin, that is, diminished effectiveness of insulin in reducing blood glucose levels. "We describe our 8-year clinical experience with metreleptin in a Brazilian adult female patient with congenital generalized lipodystrophy type 2 (due to a mutation in the BSCL2 gene) and severe insulin resistance." (PMID 40860570, 2025). "Mutations in the BSCL2 gene cause human congenital lipodystrophy, an autosomal recessive genetic disease characterized by almost complete loss of adipose tissue, insulin resistance, and fatty liver." (PMID 33964879, 2021). "BSCL2 is an autosomal recessive disorder, which is characterized by the severe loss of adipose tissue, hypertriglyceridemia, fatty liver and insulin resistance." (PMID 34409079, 2021). "Most of the patients presented BSCL2 mutation, insulin resistance, and hypertriglyceridemia." (PMID 31303898, 2019). "There is evidence to support this, as re-establishing Bscl2 selectively in adipose tissue of Bscl2 null mice is capable of restoring significant adipose mass as well as preventing insulin resistance and severe hepatic steatosis." (PMID 30552349, 2018). "In spite of this, mouse fully differentiated BAT with BSCL2 gene deletion displayed altered thermogenic capacity and some insulin resistance." (PMID 30402103, 2018). "In addition, for AGPAT2 and BSCL2 KO mice, leptin replacement or AT surgical implantation strongly improved the metabolic phenotype including insulin resistance, liver steatosis and renal injuries." (PMID 35250856, 2022). "Loss-of-function mutations in BSCL2 are responsible for Berardinelli-Seip congenital lipodystrophy, a rare disorder characterized by near absence of adipose tissue associated with insulin resistance." (PMID 27748422, 2016). "Additionally, QUICKI analysis revealed that the additional loss of hepatic Bscl2 had failed to induce insulin resistance in male or female AAV-TBG-iCre mice compared to their AAV-TBG-eGFP injected littermate controls." (PMID 31848133, 2020). "Numerous genes are candidates for severe insulin resistance, such as INSR, BSCL2, AGPAT2, CAV1, and PTRF." (PMID 33995269, 2021). "Bscl2 null mice exhibit insulin resistance and almost all other phenotypic characteristics of CGL2 patients, with the exception of hypertriglyceridemia, although this is also observed with Bscl2 null mice also lacking the low density lipoprotein receptor." (PMID 29459250, 2018).